Y_RNA (Y RNA )
Gene: Miscellaneous RNA gene on chromosome 17 (67,408,774 to 67,408,881, reverse strand). Ensembl gene ENSG00000201547.
Homologues: Orthologues: chimpanzee Y_RNA (98% identical). Paralogues in human: RNY1 (88% identical), RNY1P11 (86% identical), Y_RNA (86% identical), Y_RNA (85% identical), Y_RNA (84% identical), RNY1P8 (83% identical), Y_RNA (83% identical), Y_RNA (82% identical), RNY1P12 (81% identical), Y_RNA (81% identical), RNY1P10 (81% identical), RNY1P13 (80% identical), and 94 more.